PINK1 (PTEN induced kinase 1)
Diseases named in the same sentence as PINK1 in open-access papers (continued):
Sharing a sentence is not in itself a finding about the gene and the disease.
osteoporosis (9 papers, 2020 to 2026). A condition of reduced bone mass, with decreased cortical thickness and a decrease in the number and size of the trabeculae of cancellous bone (but normal chemical composition), resulting in increased fracture incidence. "Conversely, Pink1 deficiency in BMSCs was sufficient to induce osteoporosis." (PMID 41990575, 2026). "Together, these data indicated that WAC deletion leads to impaired bone formation in vivo and WAC and PINK1 are effective targets for the treatment of osteoporosis and bone defects." (PMID 39555688, 2025). "Our investigation extended to evaluate the potential of WAC and PINK1 as novel targets for the treatment of osteoporosis and bone repair." (PMID 39555688, 2025). "We revealed a WAC deficiency in osteoporosis and uncovered the role of WAC in promoting MSC osteogenesis via PINK1‐mediated mitophagy." (PMID 39555688, 2025). "Accordingly, we believe that PINK1 is a highly potential target for the treatment of bone metabolism‐related diseases such as osteoporosis and bone defect, and deserves further efforts to explore its application value in clinical treatment." (PMID 39555688, 2025). "This intervention demonstrated a reversal of impaired bone defect repair in WAC‐CKO mice, emphasizing the potential of WAC and PINK1 as key targets in both osteoporosis treatment and bone restoration." (PMID 39555688, 2025). "The study elucidates the mechanism by which WAC modulates MSC osteogenesis, binds to PINK1 to protect it from ubiquitination, and identifies potential therapeutic targets for osteoporosis and bone defect repair." (PMID 39555688, 2025). "For instance, reduced expression of PINK1 has been observed in patients with osteoporosis, while ovariectomized mice with PINK1 gene defects exhibited significantly decreased bone mass." (PMID 38370357, 2024). "It is noteworthy that PINK1 expression was downregulated in bones from patients with osteoporosis, which supports the practical roles of PINK1 in human bone diseases." (PMID 34823575, 2021). "To confirm the clinical relevance of PINK1 as an osteoporotic marker, we identified the expression of PINK1 in bone tissues using frozen bone samples from patients with osteoporosis." (PMID 34823575, 2021). "In order to explore the potential of targeting WAC and PINK1 to mitigate the progression of osteoporosis and promote bone formation, we designed the bone‐targeting recombinant adeno‐associated virus 9 (rAAV9) for the specific overexpression of WAC and PINK1 in bone tissue." (PMID 39555688, 2025). "We only examined PINK1/Parkin, which has a close relationship with osteoporosis." (PMID 35681421, 2022). "Furthermore, PINK1 expression was reduced in bones from patients with osteoporosis, which supports the practical role of PINK1 in human bone disease." (PMID 34823575, 2021). "Furthermore, we examined the level of PINK1 expression in patients with osteoporosis." (PMID 34823575, 2021). "We established osteoporosis models by OVX in Wild-type C57BL/6 mice (WT) and Pink1−/− mice and analyzed their bone parameters at 4 weeks after surgery." (PMID 34823575, 2021). "Clinical relevance of PINK1 expression levels was determined via qRT-PCR analysis in normal and osteoporosis patients." (PMID 34823575, 2021).
chronic kidney disease (8 papers, 2018 to 2025). Impairment of the renal function secondary to chronic kidney damage persisting for three or more months. "Pioglitazone can repair mitochondrial dysfunction induced by uraemia by upregulating PINK1 expression, inhibiting mitochondrial fusion and promoting mitophagy, thus reducing the degree of damage associated with chronic kidney diseases (CKDs)." (PMID 35962179, 2022). "Accumulating evidence suggests an impairment of PINK1/Parkin mitophagy pathway in acute and chronic kidney disease." (PMID 34359852, 2021). "For example, melatonin could enhance PINK1–Parkin-dependent mitophagy, thereby improving mitochondrial function and protecting against kidney injury in chronic kidney disease." (PMID 40423411, 2025). "The results indicated that regulation of PINK-1 may be the key factor for stem cell therapy in chronic kidney disease." (PMID 30250007, 2018). "Magnoflorine was found to promote Parkin/PINK1-mediated mitochondrial autophagy, thereby inhibiting NLRP3/Caspase-1-mediated pyroptosis, ultimately decreasing tubular cell steatosis, lipid deposition, tubular dilation, and glomerular fibrosis in chronic kidney disease." (PMID 40520024, 2025). "For example, overexpression of ATF3 represses PTEN-induced putative kinase 1 (PINK1) gene transcription in lung epithelial cells, while ATF3/c-Jun complex stimulates cannabinoid receptor type 1 (CB1R) transcription in chronic kidney disease (CKD)." (PMID 33921748, 2021).
colitis (8 papers, 2021 to 2026). Inflammation of the colon. "CPT1A downregulation exerts protective effects on DSS-induced colitis by suppressing PPARα signaling while also modulating PINK1-mediated mitophagy and reducing cellular ROS generation, thereby alleviating tissue damage induced by oxidative stress." (PMID 41563994, 2026). "To delineate the transcriptomic impact of PINK1 deficiency during colitis, we performed RNA‐seq on colonic tissues from WT + DSS and PINK1−/− + DSS mice." (PMID 40903840, 2025). "To assess the physiological relevance of ATF7‐mediated regulation of mitophagy in vivo, we employed DSS‐induced acute colitis models in intestinal epithelial cell‐specific ATF7‐deficient and PINK1‐deficient mice." (PMID 40903840, 2025). "Western blotting showed that the mitophagy-associated proteins PINK1, Parkin, and LC3B were significantly upregulated in experimental colitis, but ARRB1 KO inhibited the upregulation of these proteins." (PMID 39246845, 2024). "Palmatine protected mice against DSS-induced colitis by facilitating PINK1/Parkin-driven mitophagy and thus inactivating NLRP3 inflammasomes in macrophage." (PMID 36647064, 2023). "In addition, Spe enhanced mitophagy in colitis mice by increasing expressions of mitophagy factors (PINK1, Parkin, LC3-II) in DSS-treated mice." (PMID 41900936, 2026). "In vivo, intestinal epithelial cell‐specific knockout of ATF7 or PINK1 exacerbated dextran sulfate sodium‐induced colitis, with greater epithelial injury, elevated cytokine production, and transcriptional activation of TNF, NF‐kappaB, and inflammatory bowel disease signalling pathways." (PMID 40903840, 2025). "Furthermore, in two mouse models of colitis-associated CRC, PINK1 disruption increased TNFα, IL-1β, IL-6, and IFN-β mRNA expression, and increased colon tumorigenesis, suggesting a role for PINK1 as a tumor inhibitor in CRC." (PMID 36499214, 2022). "In addition, the induction of PTEN-induced putative kinase 1 (PINK1)/Parkin-driven autophagy was shown to protect against DSS-induced colitis through the inactivation of the NLR family pyrin domain containing 3 (NLRP3) inflammasome in macrophages." (PMID 34899362, 2021). "To validate these observations in a physiologically relevant context, we utilised intestinal epithelial cell‐specific knockout mouse models for ATF7 and PINK1, employing the DSS‐induced colitis model." (PMID 40903840, 2025).
diabetic cardiomyopathy (8 papers, 2018 to 2024). Diabetic cardiomyopathy is a disorder of the heart muscle in people with diabetes. "BRD4 is a transcriptional and epigenetic regulator which is mechanistically linked to PINK1-Parkin mediated mitophagy in diabetic cardiomyopathy." (PMID 34440882, 2021). "Higher BRD4 and lower PINK1 protein expression was observed in a mouse model of high-fat diet-induced diabetic cardiomyopathy." (PMID 34440882, 2021). "This led us to explore whether other SGLT2i, particularly canagliflozin, which has received less attention, could exert their protective effects on diabetic cardiomyopathy through enhancing mitophagy, especially the PINK1-Parkin-dependent pathway." (PMID 39000117, 2024). "In diabetic cardiomyopathy, JQ1 improved mitochondrial function and restored cardiac function and structure via PINK1/Parkin-mediated mitophagy activation." (PMID 37237996, 2023).
steatosis (8 papers, 2020 to 2025). Increased lipid within the cytoplasm of cells. "This indicated that PCELNs mitigated steatosis in hepatocytes by promoting PINK1/Parkin-mediated mitophagy." (PMID 40076875, 2025). "The effect of taurine on mitochondrial autophagy was also detected by the protein levels of LC3B, PINK1, and p62 in the steatosis LO2 cells." (PMID 37373507, 2023). "For example, cyanidin-3-O-glucoside has been shown to reduce oxidative stress, inhibit NLRP3 activation, and alleviate steatosis in HFD-induced models by upregulating PINK1–Parkin expression and enhancing their mitochondrial localization, thereby promoting PINK1-mediated mitophagy." (PMID 41391771, 2025). "The present results showed a decrease in the expression of Beclin-1, PINK1, Parkin, LC3-I, and LC3-II in both the FLHS hens and steatosis hepatic cells, indicating that the autophagy scavenging mechanism was weakened by steatosis in the hepatic cells." (PMID 37373507, 2023). "ZNF143/NEAT1/SND1-mediated ROCK2 signalling upregulation was associated with the downregulation of mitophagy proteins PTEN-induced kinase 1 (PINK1) and Parkin, suggesting that NEAT1 overexpression may contribute to steatosis by impairing mitochondrial repair mechanisms." (PMID 39872125, 2024).
synucleinopathy (8 papers, 2017 to 2026). A neurodegenerative disease that is characterized by the abnormal accumulation of aggregates of alpha-synuclein protein in neurons, nerve fibers or glial cells. "BAP31 deficiency exacerbates α-synucleinopathy-associated neurodegeneration by disrupting mitochondrial fission–fusion dynamics, impairing PINK1–Parkin-mediated, amplifying dopaminergic neuron loss." (PMID 41597212, 2026). "Although mutations in genes such as LRRK2, PINK1 and DJ-1 have often been implicated in the pathophysiology of synucleinopathies, GBA1 mutations are the ones showing the highest prevalence." (PMID 28835999, 2018). "Mitochondrial dysfunction is prevalent in synucleinopathies as evidenced by clinical findings in patients with PD/DLB who carry genetic mutations of genes LRRK2 and PINK1 which are associated with mitochondrial function." (PMID 28283027, 2017). "Therefore, combining information from an MIBG scan and genetic testing for PARKIN, PINK1, LRRK2 and other PD‐related mutations could have high predictive value for the presence or absence of synucleinopathy." (PMID 30586214, 2019).
viral infection (8 papers, 2017 to 2025). "(II) The impaired response of Pink1−/−-deficient cells against polyI:C suggests a vulnerability towards viral infections." (PMID 28768533, 2017). "In addition, PINK1 interacts with Yes-associated protein 1 (YAP1) upon viral infection and impairs YAP1/IRF3 complex formation." (PMID 31139191, 2019). "In addition, knockout of PINK1 in alveolar type 2 AECs leads to an abnormal mitochondrial morphology and an increased susceptibility to fibrotic lung remodeling following viral infection, while changes in PINK1 expression and mitophagy are observed in IPF type 2 AECs." (PMID 39668579, 2025). "Our data reveal molecular insights into how VZV gE manipulates PINK1/Parkin-mediated mitophagy to evade the host’s innate immune response and enhance viral infection in human skin models." (PMID 38184594, 2024). "The virus infection led to the downregulation of PINK1 expression and enhanced the mitophagy flux with a concomitant decline in the mitochondrial mass." (PMID 35604158, 2022). "Altogether, these data provided robust evidence for JEV-NS4A interaction with PINK1 during the virus infection." (PMID 35604158, 2022). "Our results showed that PINK1 promoted TRAF3 expression upon viral infection, likely due to PINK1-mediated Parkin degradation and repressed Parkin-mediated TRAF3 K48-linked ubiquitination, leading to decreased TRAF3 degradation." (PMID 31139191, 2019). "PINK1 positively regulates the antiviral immune response through enhanced association with TRAF3 and IRF3 upon virus infection, which promotes IRF3 phosphorylation and results in increased IFN-β and IL-6 transcription." (PMID 31139191, 2019). "Interestingly, it has been shown that viral infection downregulates PINK1 expression in macrophages and that PINK1 knockdown results in decreased cytokine production and attenuated IRF3 and NF-κB activation upon viral infection." (PMID 40479570, 2025). "In our experiments, we noted the downregulation of PINK1 protein following the virus infection." (PMID 35604158, 2022). "Considering that PINK1 binds IRF3 after viral infection in macrophages, we speculate that YAP1 might be involved in the PINK1-mediated antiviral innate immune response." (PMID 31139191, 2019). "Here, we report that viral infection down regulates PINK1 expression in macrophages." (PMID 31139191, 2019). "PINK1 knockdown results in decreased cytokine production and attenuated IRF3 and NF-κB activation upon viral infection." (PMID 31139191, 2019). "Moreover, ZIKV promotes both PINK1/Parkin-dependent and -independent pathways, as shown by increased protein levels of PINK1 and the mitophagy receptors BNIP3 and NIX during viral infection." (PMID 40622847, 2025).
cervical cancer (7 papers, 2011 to 2026). A primary or metastatic malignant neoplasm involving the cervix. "Notably, NDP52 and OPTN, besides TAX1BP1, are the major receptors mediating PINK1-mediated mitophagy in human cervical cancer cell line (HeLa)." (PMID 35305662, 2022). "Furthermore, PINK1 can directly induce metformin and arsenic trioxide synergy in cervical cancer." (PMID 37833780, 2023).
diabetic retinopathy (7 papers, 2019 to 2025). "Notoginsenoside R1, known as another important component of PNS, also induced autophagy via activating PINK1, subsequently alleviated retinal vascular degeneration in diabetic retinopathy mice." (PMID 35003304, 2021). "In particular, functional impairment of mitophagy-related proteins such as PINK1 (PTEN-induced kinase 1), Parkin and Optineurin has been shown to occur in both glaucoma and diabetic retinopathy." (PMID 35629305, 2022).
gastric cancer (6 papers, 2022 to 2024). A primary or metastatic malignant neoplasm involving the stomach. "Loss of PINK1 restrained mitophagy, facilitated the Warburg effect, and promoted macrophages polarization in gastric cancer." (PMID 37700273, 2023). "We have previously reported that ciclopirox (CPX), an antifungal drug, activates mitophagy-related proteins, such as PINK1 and Parkin, in gastric cancer cells." (PMID 39487118, 2024). "In addition, PINK1.AS promoted gastric cancer progression by sponging miR-200a to negatively regulate the expression of G Protein Subunit Alpha I1 (Gαi1) expression." (PMID 38326441, 2024). "In conclusion, all these data suggest that AMPK signaling may participate in the metformin-induced mitophagy, and metformin facilitates cisplatin resistance through AMPKα/PINK1/Parkin axis in gastric cancer cells." (PMID 36387221, 2022).
osteosarcoma (6 papers, 2023 to 2025). A usually aggressive malignant bone-forming mesenchymal neoplasm, predominantly affecting adolescents and young adults. "Through bioinformatics analysis, we found that high expression of PINK1 was associated with poor prognosis in patients with osteosarcoma, and PINK1 inhibited apoptosis and promoted proliferation pathways." (PMID 36823640, 2023). "Its high expression was associated with poor prognosis in patients with osteosarcoma, which may be related to the inhibition of PINK1 on the apoptosis pathway and the promotion of the proliferation pathway." (PMID 36823640, 2023). "Based on the bioinformatics analysis and the results of other experiments, we demonstrate that PINK1 is upregulated in osteosarcoma at the protein and mRNA levels, suggesting that PINK1 plays an important role in the development of osteosarcoma." (PMID 36823640, 2023). "To establish the expression of PINK1 in osteosarcoma cells, we collected 20 pairs of osteosarcoma tissue samples and the corresponding adjacent samples." (PMID 36823640, 2023). "Collectively, both Sorafenib and Regorafenib inhibited lung metastasis of osteosarcoma by inducing PINK1 to target the lysosomal degradation of Rab22a‐NeoF1 fusion protein." (PMID 36529692, 2023). "Altogether, we demonstrate that PINK1 plays a critical role in osteosarcoma and constitutes a potential therapeutic target for osteosarcoma." (PMID 36823640, 2023). "Collectively, our findings demonstrate that PINK1 is crucially involved in osteosarcoma and suggests that it can promote the apoptosis of OS cells as the downstream target gene of cisplatin." (PMID 36823640, 2023). "CCK-8 and clonogenic assays showed that the knockdown of PINK1 decreased the growth of U2OS osteosarcoma cells." (PMID 36823640, 2023). "Consistently, by upregulating PINK1, Sorafenib and Regorafenib can inhibit osteosarcoma lung metastasis induced by Rab22a‐NeoF1." (PMID 36529692, 2023). "Altogether, these results indicate that FOXO3a modulates the overexpression of PINK1 in osteosarcoma cells." (PMID 36823640, 2023). "This study was designed to analyze the mechanism by which PINK1 affects osteosarcoma using bioinformatics and cell experiments." (PMID 36823640, 2023). "The knockdown of PINK1 reduced cell proliferation, and PINK1 silencing induced apoptosis in U2OS osteosarcoma cells." (PMID 36823640, 2023). "PINK siRNA- or control siRNA-transfected U2OS cells were used as an in vitro model to explore the biological function of PINK1 in osteosarcoma." (PMID 36823640, 2023). "Considering the effect of GABARAP on mitophagy in osteosarcoma, we next explored the expression of several key mitophagy-associated genes, including BNIP3, PINK1, Parkin, LC3B, p62, and Beclin1, which were significantly downregulated in GABARAP knockdown cells." (PMID 41346635, 2025). "Two targeted drugs, Sorafenib and Regorafenib, could upregulate PINK1 to diminish osteosarcoma lung metastasis induced by Rab22a‐NeoF1." (PMID 36529692, 2023). "Interestingly, we found that the level of PTEN in osteosarcoma was significantly lower than that in adjacent tissues, which is contrary to the elevated PINK1 expression." (PMID 36823640, 2023). "Next, we found that both PINK1 mRNA and protein levels were upregulated in osteosarcoma tissues." (PMID 36823640, 2023). "More importantly, by two screenings of the kinase library and kinase inhibitors library, we discovered that Sorafenib and Regorafenib as multi‐kinase inhibitors diminished osteosarcoma lung metastasis induced by Rab22a‐NeoF1 fusion protein via the PINK1/Rab22a‐NeoF1 axis." (PMID 36529692, 2023). "Altogether, these results indicate that silencing PINK1 inhibits osteosarcoma cell proliferation." (PMID 36823640, 2023). "Silencing of PINK1 suppresses osteosarcoma cell proliferation." (PMID 36823640, 2023). "Our results reveal that PINK1 is a prospective novel target for osteosarcoma treatment." (PMID 36823640, 2023).